TLR4 (toll like receptor 4)
Diseases named in the same sentence as TLR4 in open-access papers (continued):
Sharing a sentence is not in itself a finding about the gene and the disease.
tumor (continued). "The bacterial LPS will be recognized as an immunogenic PAMPs by PRRs to promote the M1 polarization of TAMs and induce the maturation of immature DCs (iDCs) via the TLR4–MyD88–NF-κB pathway, finally activating T effector cells and triggering the integrated immunity to kill tumor cells." (PMID 36381212, 2022). "Accordingly, we also detected the phosphorylation of NF-κB and the high expression of its downstream Cox-2 in tumor cells with TLR4 activation, suggesting that this signaling pathway still contributes to perpetuate proliferation signaling after cancer development, as observed by high levels of IL6R." (PMID 35327577, 2022). "Intra-tumour microbiota observed in OS may contribute to control the tumour development and consequently TLR4 activation by specific agonists may represent a potential therapeutic opportunity to stimulate the immune response against cancer cells." (PMID 35990515, 2022). "Dieckol and phlorofucofuroeckol reduced the migration and invasion of tumoral cells, as well as decreased the expression of receptor 4 (TLR-4) and NF-κB promoter-driven transcriptional activity, which is essential for cells proliferation, migration, tumor growth and inflammation." (PMID 35736190, 2022). "Targeting MDSC mobilization via CXCL10/TLR4 signaling could not only protect the liver graft from IRI but also reduce tumor recurrence after transplantation." (PMID 35634295, 2022). "Interestingly, activation of TLR4 by lipopolysaccharide (LPS) upregulates programmed death ligand 1 (PD-L1), which is favorable for tumor cells in driving T cell exhaustion, thus contributing to immune escape." (PMID 36389785, 2022). "Similarly, the KGM- and 5-FU-induced decrease in tumor weight was significantly reversed by TLR4 overexpression." (PMID 37304412, 2022). "While our study is consistent with previous studies that investigated TLR4 expressed on cancer cells which report the involvement of TLR4/MyD88 in tumor progression, the involvement of the TLR4/TRIF pathway in tumor progression is not well-supported in the literature." (PMID 36232715, 2022). "In the instance of secreted cathepsin K, it could also polarize M1 macrophages to M2 through TLR-4 processing and activation, which is viewed as an important aspect of M2 macrophage–tumor cross talk for EMT progression of cancer cells." (PMID 34918208, 2022). "Paclitaxel also binds to Toll-like receptor 4 (TLR-4), activating TLR-4 downstream signaling pathways that lead to the synthesis of many proinflammatory mediators during inflammation, some of which are crucial in carcinogenesis and tumor growth." (PMID 36555406, 2022). "Similarly, tumor-derived fibronectin ED-A stimulates platelet aggregation and thrombosis through TLR4 and promotes platelet-induced NETosis." (PMID 35936717, 2022). "Notably, western blotting analysis was conducted on protein extraction from tumor samples and revealed significant blockage caused by TAK-242, PDTC, and YC-1 on the TLR4/NF-κB/HIF-1α signaling loop." (PMID 35464826, 2022). "Interestingly, it has been proven that the expression of TLR4 exerts a significant anti-tumor effect in DC-based immunotherapy." (PMID 35663957, 2022). "All these results demonstrate that the LPS fragments released from MRT+MH-treated Fn are capable of activating the macrophages into M1 polarization via the TLR4/MyD88/NF-κB pathway, which results in significant secretions of various cytokines against tumor cells in vitro." (PMID 36381212, 2022). "Similarly, delivery of TLR4+/+ macrophages increased tumor burdens in both WT and TLR4−/− mice, while transfer of TLR4−/− macrophages yielded the opposite effect." (PMID 36542153, 2022). "However, there has yet to be a specific TLR4 antagonist used in a tumour-bearing preclinical model to investigate the impact on GIM and tumour growth simultaneously." (PMID 35962138, 2022).
tumor (continued). "We herein hypothesized that TLR4 and pSTAT3 may be involved in tumor-immune crosstalk within the blood circulation, and that their assessment in PB could provide insights into BC progression." (PMID 35205801, 2022). "Finally, chronic inflammation within the tumor niche leads MM-MSCs to activate TLR4 signaling, which polarizes them toward a pro-tumorigenic phenotype, favoring immunosuppression and tumor growth." (PMID 35064098, 2022). "Furthermore, tumor-derived redHMGB1 was identified as the priming signal, which, through TLR4 and mTOR/AKT pathway, induced Bcl6-driven program underpinning SMMs generation." (PMID 36542153, 2022). "At the same time, we cannot overlook the role of TLR4 in tumor proliferation." (PMID 36281200, 2022). "However, MOR, DOR, and κ opioid receptors (KOR), in addition to opioid growth factor receptor (OGFR) and Toll–like receptor 4 (TLR4), have been shown to promote tumor cell migration." (PMID 35359418, 2022). "TLR4 stimulation might have both antitumor and pro-tumor consequences.Trial registration: This study was registered with ClinicalTrial.gov, number NCT02406781." (PMID 36303228, 2022). "The current study provides first evidence that TLR4 and pSTAT3 signaling on CTCs and PBMCs might play an important role in the peripheral anti-tumor response and metastatic progression of BC." (PMID 35205801, 2022). "Nevertheless, TLR4 has different roles depending on tumor type." (PMID 35468924, 2022). "We next sough to address whether resumption of Bcl6 would restore SMM generation in TLR4−/− macrophages, the population proved to be unable to induce Bcl6 upon tumor stimulation." (PMID 36542153, 2022). "Extracellular HMGB1, released from the tumor cells under hypoxia, mediates communication between cells in the tumor microenvironment through binding several receptors, especially RAGE and TLR4, which contribute to tumor growth via sustenance of long-term inflammation." (PMID 36012593, 2022). "Both TLR2 and TLR4 are expressed on the surface of innate myeloid cells, such as macrophages and dendritic cells, but also endothelial and epithelial cells, and are key initiators of the innate anti-tumour immune response." (PMID 36499361, 2022). "Resistin is a type of cysteine-rich polypeptide hormone that functions through its purported receptor, Toll-like receptor 4 (TLR4), which plays a critical role in regulating inflammation and is also involved in tumor cell proliferation, invasion and metastasis." (PMID 36497484, 2022). "In summary, tiRNA-Gly-GCC-1 could promote tumor progression and inhibit TLR4 expression by directly targeting its 3′UTR." (PMID 36230476, 2022). "This could be due to the differences in the injury induced (skin vs. ear) and therefore, it would be interesting in future work to determine if PRG4 treatment could influence full thickness skin injuries and if TLR4 had any impact on this effect." (PMID 35750773, 2022). "We also wanted to test whether TLR4 antagonism modulated CRC tumour growth and response to CPT-11 in our model." (PMID 35962138, 2022). "The correlation between TLR4 and neoplasms has been of great interest, but discrepancies remain." (PMID 36281200, 2022). "However, it should be pointed out that various cancers can have different degrees of TLR-4 contribution in tumorigenesis or tumor progression." (PMID 36142391, 2022). "Furthermore, we also observed that the degree of negative correlation was increased, when we reanalyzed S100A7 and TLR4 expression only in malignant tumor tissues." (PMID 33969603, 2022). "TLR4-induced TGF-β expression has also been associated with the transformation of fibroblast into cancer-associated fibroblast (CAF) in the tumor microenvironment, facilitating cancer cell proliferation and tumor growth." (PMID 35780158, 2022).
tumor (continued). "TLR4 is a typical receptor from the Toll-like receptors (TLRs) family that is expressed on both immune cells and tumor cells, and its overexpression may lead to cancer progression." (PMID 36071472, 2022). "Nevertheless, it is acknowledged that the TME is a complex ecosystem and the Lap-induced ICD of tumor cells may also activate TLR4 signaling in DCs to stimulate antitumor immune responses." (PMID 36167857, 2022). "Likewise, most ICD-related genes, including IL-6, IL-10, NLRP3, CD8A, CD8B, and TLR4, exhibited attenuated expression levels in tumor cells compared to normal cells." (PMID 36225939, 2022). "Moreover, NET-derived NE was shown to enhance tumor cell growth and mitochondrial biogenesis via the interaction with TLR4 on cancer cells." (PMID 36555469, 2022). "Additionally, high-mobility group box 1 (HMGB1) proteins derived from dead tumor cells trigger toll-like receptor 4 (TLR4) on DCs to produce type I IFNs through myeloid differentiation factor 88 (MyD88) signaling." (PMID 35292881, 2022). "The results of this study enhanced our understanding of the mechanism of PAUF-induced tumor-promoting effects and suggests that TLR4 expression on cancer cells may be an important biomarker for anti-PAUF treatment." (PMID 36232715, 2022). "Furthermore, lipopolysaccharide stimulation of platelets or tumor-derived factors via TLR4 enhances platelet-neutrophil adhesion and induces NETosis, but does not promote platelet aggregation or upregulate P-selectin expression." (PMID 35936717, 2022). "F. nucleatum lipopolysaccharide leads to strong induction of the TLR4/MYD88 innate immune signaling pathway to regulate miRNA expression, and the expression of specific miRNAs can promote tumor proliferation and the development of chemoresistance through the TLR4/MYD88 pathway." (PMID 35198889, 2022). "TLR4 is the most frequently reported oncogenesis and tumour growth gene." (PMID 35801728, 2022). "Accordingly, several studies have shown that LPS activation of TLR4 accelerates tumor growth." (PMID 35197571, 2022). "Importantly, HCC cells with elevated TLR4 expression are sensitive to TLR4-mediated tumor promotion through the activation of Akt, NF-κB and STAT3 signaling and the downregulation of let-7 miRNA." (PMID 35955552, 2022). "Moreover, a previous study indicated that miR-145 upregulation sensitizes HCC cells to 5-FU and enhances the 5-FU-induced inhibition of HCC tumor growth by targeting TLR4." (PMID 37304412, 2022). "Moreover, the interaction between calreticulin and toll-like receptor 4 (TLR4) expressed on tumor cell surface promotes the secretion of TNFα and CCL19, which facilitates the migration and maturation of DCs, to limit the tumor progression in vivo." (PMID 36703971, 2022). "Another study showed that TLR4 activated the AKT pathway in tumour development." (PMID 34953035, 2022). "Activation of TLR-4 may increase the production of factors that promote tumor development via the MyD88 pathway." (PMID 36520928, 2022). "One explanation could be that low or high activation levels of TLR4/MyD88 signaling lead to significantly different expression levels of specific TLR4/MyD88 target genes, which in turn would affect the tumor infiltration capacity in opposing ways." (PMID 36224342, 2022). "Toll-like receptor 4 (TLR4) is a lipopolysaccharide receptor that may influence tumor progression through inflammatory response and immune response." (PMID 36281200, 2022). "In addition, all tumor cell lines included in our experiments have been shown to express TLR4 —a fact that supports the connection between the detected antitumor effects and XOS–TLR4 interaction." (PMID 36142342, 2022). "For example, certain microbes with anti-tumor effects, such as Bacteroides thetaiotaomicron and B. fragilis can activate dendritic cells through Toll-like receptor (TLR)-4 signaling and promote Th1 and cytotoxic CD8+ T cell responses helpful for the tumor immunosurveillance and eradication." (PMID 36310871, 2022).
tumor (continued). "CXCR7, but not CXCR4, expression can be increased by lipopolysaccharide treatment in cells expressing both TLR4 and the MD2 coreceptor; additionally, in patients, high expression of TLR4, MD2 and CXCR7 is associated with tumor cell infiltration in lymph nodes and distant metastases." (PMID 35406582, 2022). "TLR4/NF-κB signaling pathway can activate the innate immune system, promote dendritic cell maturation, upregulate the expression of macrophages, and cause the production of TNF-α, IL-6, IL-12, IL-1β, and CCL5, as well as mediate tumor cell apoptosis." (PMID 36204132, 2022). "Taken together, our findings illustrate an innovative concept that a probiotic-derived siderophore can reprogram the pancreatic TME through TLR4, which is permissive to improve tumor immune surveillance and responsiveness to immune checkpoint inhibitors immunotherapies." (PMID 36333531, 2022). "However, while TLR4 shows mostly pro-tumor effects, it can also result in interferon expression and secretion, which can induce an anti-tumor response." (PMID 35327577, 2022). "The implication of TLR4 in the morphine-mediated modulation of cancer initiation and progression has been unexplored so far, although this receptor is expressed on multiple cellular components of the tumor microenvironment." (PMID 35565382, 2022). "Our findings indicated that TMED2 knockdown significantly inhibited the development of LUAD by increasing apoptosis, inhibiting tumor cell proliferation, reducing tumor volume, and decreasing the levels of tumor biomarkers and inflammatory factors by affecting the TLR4/NF-κB signaling pathway." (PMID 35135563, 2022). "Additionally, our data reveal that tumor-derived redHMGB1 serves as the priming signal to be sensed by TLR4 and initiate the mTOR/Bcl6-driven program for SMMs development." (PMID 36542153, 2022). "In addition, it has been shown that the TLR4 signaling pathway of tumor cells is basically the same as that of immune cells." (PMID 35965618, 2022). "Taken together, our results demonstrate TLR4 upregulation in OSCC, which can be associated with the cancer inflammatory microenvironment, since its expression increases when a lichenoid infiltrate surrounds the tumor." (PMID 35327577, 2022). "Collectively, our data demonstrated that TLR4 played a non-intrinsic role in promoting cancer progression, which was likely associated with compromised anti-tumor immunity." (PMID 36542153, 2022). "In addition, it was revealed that TLR4 is a tumor stem cell marker, whose abnormal expression induces stem cell-like characteristics by activating the TLR4/Nanog pathway." (PMID 35965618, 2022). "Interestingly, NEMO∆hepa/Tlr4−/− mice displayed a reduced abundance of MDSCs and an increase in CD4+ T cells, which was linked to a lower tumor burden at 52 weeks." (PMID 35803930, 2022). "During cellular stress, S100A8 and S100A9 is released as a heterodimer (e.g., calprotectin) into the extracellular space where it binds to TLR4 and initiate a signaling cascade that regulates inflammation, cell proliferation, differentiation, and tumor development in an NF-κB-dependent manner." (PMID 33679877, 2021). "In addition, both PTX and nab-PTX induce the reprogramming of M2 macrophages to the M1 phenotype in a TLR4-dependent manner, thus reducing tumor growth." (PMID 34885065, 2021). "Thereby, IECs might not only stimulate their own TLR4 expression but ongoing proliferation could also promote tumor formation." (PMID 34025672, 2021). "TLR4 signaling pathway is a classic regulatory pathway, polysaccharides promote the production of cytokines, regulate immune response and anti-tumor by activates the cascade of immunoregulation pathway and key downstream transcription factors, such as MyD88 and NF-κBs." (PMID 34641277, 2021).
tumor (continued). "Because M3G directly bound to TRL4 in glial cells, and the activation of TLR4 in tumor cells modulated PD-L1 expression, we further examined whether the upregulation of PD-L1 in A549 and H1299 cells by M3G was mediated by TLR4." (PMID 33628591, 2021). "Here, we used CT26 cells and BALB/c mice to establish the CRC-bearing mouse model to examine whether TLR4 affects the tumor-infiltrating immune cell profiles under HFD conditions." (PMID 34385421, 2021). "Triptolide significantly suppressed MDA-MB-231 cell viability and clonogenic ability via inhibiting High Mobility Group Box 1 (HMGB1) mRNA expression and its associated factors, e.g., Toll-like receptor 4 (TLR4) and phosphorylated form (p) of NF-κB p65 and inhibited MDA-MB-231 tumor growth." (PMID 34948368, 2021). "LPS stimulation could induce the secretion of IL-2, TNF-α, type I interferon by activating TLR4 in dendritic cells or macrophages, and induced anti-tumor T cell activation." (PMID 34718325, 2021). "The relationship between TLR4 and tumor cell immune invasion was studied." (PMID 34631699, 2021). "In our mouse tumor recurrent model, TLR4 inhibitors could effectively reduce hepatic MDSCs and inhibit tumor growth." (PMID 33990548, 2021). "In addition, several studies have reported that TLR4-dependent TAM reprogramming into an M1 profile reduces tumor growth." (PMID 34900687, 2021). "TLR4 inhibitor (CLI095) was used to explore its therapeutic effects in tumor recurrence post IRH." (PMID 33990548, 2021). "In particular, more and more evidences have shown that the TLR4-mediated signaling might act as a pivotal pathogen-activated tumor signal pathway and an important carcinogenic mechanism involved in the development of CAC." (PMID 34479599, 2021). "TLR4 inhibition in immune-competent individuals could not only reduce ERG function but also relieve suppression of the immune system in the tumor." (PMID 33554122, 2021). "TLR4 is increasingly recognised as playing key roles in tumour biology and anticancer defences." (PMID 34771442, 2021). "Aberrant TLR4 activation in the cancer environment can support tumor growth." (PMID 33923020, 2021). "Moreover, experiments in different mouse models indicated that either TLR4 deletion protected TLR4-/- mice from tumor development or epithelial overexpression of TLR4 promoted inflammatory responses and tumorigenesis in CAC." (PMID 34025672, 2021). "Next, we addressed how TNC induced Cxcl12 by using inhibitors according to established protocols for tyrosine kinase inhibitors (sunitinib), integrin α4β1 and α9β1 (BOP), TGFβ receptor 1 (TGFβRI, GW788388), and Toll‐like receptor 4 (TLR4, Cli95) on tumor cells stimulated with TNC." (PMID 33988305, 2021). "Since the high expression level of TLR-4 is a kind of biomarkers of M1 macrophages 28, HMGB1 released from irradiated BCCs might assist in the anti-tumor activation of macrophages through TLR-4 pathway." (PMID 33867819, 2021). "It deserves further investigation to examine whether under HFD conditions, activation of TLR4 reduces NK cell infiltration into the tumor tissues, which may also suggest how HFD promotes CRC growth." (PMID 34385421, 2021). "Contemporary literature indicates that opioids can be active at TLR4; however, whether this contributes to the action of opioids on tumour growth and metastasis is, to date, entirely unexplored." (PMID 34771442, 2021). "In addition, polyethyleneimine, cationic dextran, and multiwalled carbon nanotubes also activated TLR4 signal in TAMs leading to reversed M2-like phenotypes and reduced tumor burden possibly through NF-κB." (PMID 33990205, 2021). "Because M3G can activate the TLR4 pathway, it is important to determine whether M3G can regulate the PD-L1 expression through the TLR4 expressed in tumor cells, to boost tumor progression." (PMID 33628591, 2021).